HDAC6 (histone deacetylase 6)
Diseases named in the same sentence as HDAC6 in open-access papers (continued):
Sharing a sentence is not in itself a finding about the gene and the disease.
lung carcinoma (continued). "The suppression of migration and invasion activities of honokiol was through inhibiting HDAC6‐mediated Hsp90/MMP‐9 interaction and followed by MMP‐9 degradation in lung cancer." (PMID 32180962, 2020). "Accordingly, the results suggested that the suppression of migration and invasion activities by honokiol was through inhibiting HDAC6‐mediated Hsp90/MMP‐9 interaction and followed by MMP‐9 degradation in lung cancer." (PMID 32180962, 2020). "In lung cancer samples, we also observed a significant overexpression of HDAC1, HDAC2, HDAC6 and also DNMT1 and DNMT3A." (PMID 28634396, 2017). "Compounds 9a-d selectively inhibited HDAC6 (IC50 = 0.1–1.0μM) over HDAC1 (IC50 = 0.9–6μM) and moreover, also selectively inhibited the growth of lung cancer cells vs. patient matched normal cells." (PMID 26698121, 2015). "Clinically, lung cancer patients with high HDAC1, HDAC2, and HDAC6 levels have a poor prognosis." (PMID 40732250, 2025). "In addition, pentadecanoic acid acted as a novel histone deacetylase 6 (HDAC6) inhibitor, and it promoted the acetylation of α-tubulin in MCF-7 breast and A549 lung cancer cells dose-dependently." (PMID 38633315, 2024). "Although both SIRT2 and HDAC6 bound the KRASMut protein, neither greatly affected the acetylation or activity of the KRASMut protein in lung cancer cells." (PMID 37779142, 2023). "HDAC6 is necessary for the induction of EMT after treatment with TGFβ in lung cancer and in a non-tumor cell line." (PMID 34073238, 2021). "Thus, suppression of migration and invasion is triggered by promoting HDAC6-mediated HSP90/MMP-2 or MMP-9 dissociation and followed by MMP-2 and MMP-9 degradation in breast and lung cancer cells." (PMID 32961679, 2020). "Previous studies have shown that HDAC6 knockdown inhibits EGFR expression in A549 lung cancer cell line, without affecting their growth." (PMID 29113288, 2017). "HDAC6, a primarily cytoplasmic deacetylase, mediates TGF-β1-induced EMT in human lung cancer cells." (PMID 27499032, 2016). "TBBX induced G1 cell cycle arrest might be through down-regulation HDAC6 expression and followed by hyper-acetylation of Hsp90 and accelerating cyclin D1 and CDK4 degradation in H1299 lung cancer cells." (PMID 25946558, 2015). "Moreover, the average expression level of the HDAC6 gene obtained from the GEO database (GSE27262) was significantly higher in lung cancer tissues than in adjacent nontumorous lung tissues." (PMID 36639650, 2023). "The results suggested that polyphenolic compounds of the C. macrocarpa polar fractions with elevated pose score could be used as a potential treatment for lung cancer or as a scaffold for developing new inhibitors for enzymes HDAC6 and PDK3, related to lung cancer progression." (PMID 36559012, 2022). "Furthermore, it has become more apparent how HDAC6 and PDK3 contribute to the development of lung cancer, and it is now generally accepted that the inhibitors may be used to treat lung cancer." (PMID 36559012, 2022).
prostate carcinoma (38 papers, 2010 to 2025). A carcinoma that arises from epithelial cells of the prostate gland. "High expression of HDAC6 is significantly linked to poor prognosis for the patients with prostate cancer, as well as colorectal cancer." (PMID 32888405, 2020). "Again, studies in other tumor entities revealed an ambiguous picture, with the HDAC1-, HDAC3- and HDAC6-specific inhibitor SN30028 leading to a persistent downregulation of amphiregulin in the prostate carcinoma cell line PC3." (PMID 39864337, 2025). "The performed analyses allowed the selection of eighteen compounds, four of which were active against the HDAC6 recombinant enzyme and also displayed antiproliferative activity against selected prostate cancer cell lines." (PMID 39204176, 2024). "The identified candidates were tested in vitro to determine HDAC6 and Hsp90 inhibitory activity and antiproliferative effects on PC-3 and LNCaP prostate cancer cells." (PMID 39204176, 2024). "This provides an opportunity for structural and medicinal chemistry optimization in order to obtain HDAC6/Hsp90 dual modulators with antiproliferative effects against prostate cancer." (PMID 39204176, 2024). "Compound 2–75 is an enzalutamide hybrid with HDAC inhibitory activity that promoted p21, increased acetyl-tubulin levels (due to enhanced HDAC6 inhibition), and lowered Hsp90 and AR protein levels in C4-2 prostate cancer cells." (PMID 36034650, 2022). "Smad7 is also directly involved in gene transcription in cancer cells, as the Smad7 protein can bind to specific regions in the promoter of c-Jun and histone deacetylase 6 (HDAC6) in prostate cancer cells, promoting migration and invasion." (PMID 35625561, 2022). "SMAD7 enhanced TGF-β induction of c-Jun and HDAC6 and contributed to tumor aggressiveness in prostate cancer cells." (PMID 35912252, 2022). "Belinostat (PXD101) suppressed Hsp90 activity, GSK-3β, and AR function by HDAC6 inhibition and prevented the development of castration-resistant phenotype in prostate cancer cells." (PMID 35582529, 2022). "Hormone treatment induced castration-resistant phenotype and upregulated HDAC6 expression in prostate cancer cells." (PMID 35582529, 2022). "Acetylation of Hsp90 is regulated by cytoplasmic HDACs such as HDAC6, while Hsp90 regulates AR activity and stability in prostate cancers." (PMID 35582529, 2022). "The ability of Smad7 to act as a transcription factor has been previously shown in prostatic cancer cells, where Smad7 can bind the regulatory regions and enhance the expression of c-Jun and Histone deacetylase 6, two tumor-promoting genes." (PMID 36291778, 2022). "Zeta55, a selective inhibitor of HDAC6, was reported to degrade the androgen receptor (AR) and reduce the growth of AR-overexpressing prostate cancer cells both in vitro and in a castration-resistant prostate cancer (CRPC) xenograft model." (PMID 36076996, 2022). "In this study, we show that Zeta55 can target both AR and HDAC6, and potently inhibit the tumor growth of prostate cancer in vitro and in vivo." (PMID 33621955, 2021). "In this study, we established LASSBio-1911, a potent HDAC6/8 inhibitor, and LASSBio-2208, a potent dual PI3K/HDAC6 inhibitor, as two novel therapeutic potential drugs against prostate cancer with high metastatic potential and limited treatment options." (PMID 33919077, 2021). "In prostate cancer cells, deacetylated Hsp90 binds to and stabilizes the androgen receptor (AR), while the HDAC6 suppressor sulforaphane led to increased levels of acetylated Hsp90 accompanied by enhanced AR degradation." (PMID 34959719, 2021). "To examine additional strategies increasing apoptotic cell death in prostate cancer cells we combined the HDAC6 and MEK inhibitors with PTX." (PMID 32754596, 2020). "A correlation between the mRNA expression of Smad7 and HDAC6, Smad7 and c-Jun, and c-Jun and HDAC6 was found in public databases from analyses of prostate cancer tissues." (PMID 32888405, 2020).
prostate carcinoma (continued). "From these data, we conclude that the expression of HDAC6, Smad7, and c-Jun correlates with poor prognosis for patients with prostate cancer." (PMID 32888405, 2020). "We found a positive correlation between Smad7 and c-Jun mRNA, Smad7 and HDAC6 mRNA, and c-Jun and HDAC6 mRNA in tumor material from patients with prostate cancer." (PMID 32888405, 2020). "High expression of Smad7, HDAC6, and c-Jun correlated with poor prognosis for patients with prostate cancer." (PMID 32888405, 2020). "The expression of HDAC6, Smad7, and c-Jun was examined by immunohistochemistry in tissue sections from patients with prostate cancer and in tissue sections from normal prostate gland." (PMID 32888405, 2020). "Our identification of HDAC6 as a downstream target gene of Smad7 in response to TGF-β is therefore of clinical importance for patients with prostate cancer, as HDAC6-inhibitors are currently investigated for their effects on cancer cells in clinical trials." (PMID 32888405, 2020). "Here we report an additional function of Smad7, i.e., to enhance TGF-β induction of c-Jun and HDAC6 via binding to their regulatory regions, promoting migration and invasion of prostate cancer cells." (PMID 32888405, 2020). "Selective HDAC6-inhibitors modulating Hsp90 activity have been proposed for reducing prostate cancer aggressiveness." (PMID 32754596, 2020). "The histone deacetylase 6 (HDAC6) mapped to Xp11.23 is an important AR regulator in prostatic cancer by enhancing AR protein stability." (PMID 32626651, 2020). "In summary, we have described a novel role for Smad7 as a transcriptional regulator of c-Jun and HDAC6 in prostate cancer cells, promoting migration and invasion." (PMID 32888405, 2020). "Genistein decreases HDAC6 expression, abrogating Hsp90 activity, and consequently downregulating AR and prostate cancer cell proliferation." (PMID 30627525, 2018). "Genistein also seems to be effective in the prevention of prostate cancer since it decreased androgen receptor (AR) expression in prostate cancer cells through inhibition of HDAC6-Hsp90 interaction." (PMID 30627525, 2018). "Herein, MPT0B451 induced acetyl-α-tubulin expression in both human prostate cancer cells and leukemic cells via HDAC6 activity inhibition." (PMID 29593536, 2018). "The previously reported ability of tubacin to induce DNA damage signaling in prostate cancer cells was considered to be HDAC6-dependent." (PMID 29423038, 2018). "The effects of GEN-mediated HDAC6 down-regulation on AR-signaling were mimicked by HDAC6 siRNA, thus confirming the importance of this mechanism for prostate cancer preventive potential of GEN." (PMID 25322458, 2014). "Trichostatin A, for example, disrupts the interaction between PPP1 and HDAC6 in glioblastoma and prostate cancer cells." (PMID 24629090, 2014). "HDAC6 and Heat Shock Protein 90 (Hsp90) are key regulatorswithinthe androgen response pathway, exhibiting a close interplay and mutualinteraction patterns that make their combined inhibition a promisingstrategy for treating aggressive prostate cancer (PC)." (PMID 40699153, 2025). "In this study, we devised and applied a virtual screening campaign on a large library of commercially available compounds, searching for molecules endowed with Hsp90/HDAC6 dual activity and antiproliferative activity against LNCaP and PC-3 prostate cancer cells." (PMID 39204176, 2024). "Research evidence suggests that the combined inhibition of Hsp90 and HDAC6 could yield remarkable therapeutic benefits against prostate cancer, especially in its more advanced and aggressive forms." (PMID 39204176, 2024). "Interestingly, in prostate cancer cells (LNCaP), blocking of HDAC6 with Panobinostat led to increased ERK activity and, as a consequence, promoted apoptosis." (PMID 35159049, 2022).
prostate carcinoma (continued). "Compound 2-75 is a promising enzalutamide hybrid with HDAC inhibitory activity, which induced p21, led to higher acetyl-tubulin levels (based on stronger HDAC6 inhibition) than vorinostat, and suppressed Hsp90 and AR protein levels in C4-2 prostate cancer cells." (PMID 35582529, 2022). "This suggests that genistein may be used as a potential chemoprophylaxis for prostate cancer in combination with known inhibitors of HDAC6 and Hsp90." (PMID 34530730, 2021). "In addition, several studies have reported the role of HDAC6 and Hsp90 in the treatment of prostate cancer." (PMID 34530730, 2021). "A previous study has revealed that HDAC6 interacted with FUS in prostate cancer cells." (PMID 34307380, 2021). "In the current study, we report that Smad7 promotes expression of HDAC6 in prostate cancer cells." (PMID 32888405, 2020). "The TGF-β- and Smad7-induced increases of c-Jun and HDAC6 promote invasion of prostate cancer cells, making it relevant to investigate expression of Smad7, c-Jun, and HDAC6 in clinical tissue samples of patients with prostate cancer as potential biomarkers and drug targets." (PMID 32888405, 2020). "Moreover, a high co-expression of Smad7 and HDAC6, and c-Jun and HDAC6, was observed in prostate cancer tissues, which correlated with poor prognosis." (PMID 32888405, 2020). "Moreover, a high co-expression of Smad7 and HDAC6, and c-Jun and HDAC6 was also observed in prostate cancer tissues, which correlated with poor prognosis." (PMID 32888405, 2020). "Thus, MPT0B451 is an efficient inhibitor against HDAC6 and effectively induces cytotoxicity in human prostate cancer cells and acute myeloid leukemia cells." (PMID 29593536, 2018). "In conclusion, this study suggests that HDAC6 may be a sensitive therapeutic target in the treatment of prostate cancer using LBH589 for clinical translation in future." (PMID 24023871, 2013). "This study provides pre-clinical evidence that HDAC6 may serve as a sensitive therapeutic target in the treatment of prostate cancer with HDACI LBH589 for clinical translation." (PMID 24023871, 2013). "Previously, we developed novel amide-bearing hydroxamic acid derivatives as class-selective HDAC inhibitors termed SL142 and SL325 and reported that these small molecules show more significant HDAC1, HDAC4 and HDAC6 inhibitory activity in human prostate cancer cells LNCaP than SAHA." (PMID 21079797, 2010). "Therefore, dual HDAC6/AR inhibitors are likely to produce synergistic effects that may conveniently be utilized as a new approach for the treatment of prostate cancer." (PMID 36034650, 2022). "Thus, HDAC6 appears to be a promising target for castration-resistant prostate carcinoma treatment." (PMID 32754596, 2020). "Conversely, a transient upregulation of EGFR was shown in the prostate carcinoma cell line DU-145 after treatment with the HDACi SN30028, which inhibits not only class I HDACs, but also the class IIb representative HDAC6." (PMID 39864337, 2025). "P62, a selective receptor of autophagy, increased the expression of HDAC6, promoted epithelial-to-mesenchymal transition (EMT), and enhanced the proliferation of prostate cancer cells." (PMID 36076996, 2022). "Here, the cytotoxic and antimetastatic effects of a new HDAC6/8 inhibitor, LASSBio-1911, and a new dual-PI3K/HDAC6 inhibitor, LASSBio-2208, were evaluated against PC3 prostate cancer cell line." (PMID 33919077, 2021). "For example, compound 11b, an indomethacin-SAHA fusion molecule that selectively inhibits COX2 and HDAC6 > HDAC8 > HDAC3 > HDAC2 > HDAC1, inhibits the proliferation of androgen-dependent prostate carcinoma cells." (PMID 31561534, 2019). "Although the genetic backgrounds of prostate cancer cell lines are different, LBH589 treatment induces ERK activation and HDAC6 down-regulation in 22Rv1 and DU 145 PCa cell lines other than LNCaP cells." (PMID 24023871, 2013).
prostate carcinoma (continued). "For instance, a mouse study in which the growth and invasion of prostate cancer cells, with or without knockdown of Smad7, HDAC6, or c-Jun, is missing." (PMID 32888405, 2020). "In addition to transcriptional repression of HDAC6, GEN induced expression of several HATs, including p300, PCAF, CBP, and HAT1 in LNCaP and DuPro prostate cancer cell lines and the normal epithelial prostate cell line RWPE-1." (PMID 25322458, 2014). "Indeed, Smad7 regulates expression of HDAC6 in prostate cancer in response to TGF-β53 and HDAC6 may play an indispensable role in balancing the maintenance and activation of primordial follicles through mechanistic target of rapamycin (mTOR) signaling in mice." (PMID 36402791, 2022). "Anti-tumor effects of HDAC6-specific inhibitors on prostate cancer cells have been observed; however, the role of TGF-β and its connection to HDAC6 in prostate cancer progression have not been addressed before." (PMID 32888405, 2020). "Our results showed that prostate cancer-derived SPOP mutants including Y87C, F102V, W131G, and F133L, which are located in its substrate-recognizing MATH domain, failed to bind to and promote HDAC6 degradation." (PMID 28599312, 2017).